KLF10 (KLF transcription factor 10)
Diseases named in the same sentence as KLF10 in open-access papers (continued):
Sharing a sentence is not in itself a finding about the gene and the disease.
tumor (continued). "Sirtuin 6 (SIRT6) is one of a few downstream genes that are bound by KLF10 and govern cancer metabolism and tumor progression." (PMID 34702956, 2021). "Our research suggests that FLVCR1-AS1 plays a tumor-suppressive role in PC by inhibiting proliferation, cell cycle, and migration through a positive feedback loop with KLF10, thereby providing a novel therapeutic strategy for PC treatment." (PMID 34635142, 2021). "In experiments on mouse models and human cell cultures, Hui-Ju Ch’ang at the National Institute of Cancer Research in Zhunan, Taiwan, and co-workers found that KLF10 binds to and upregulates another tumor suppressor gene, SIRT6." (PMID 34702956, 2021). "Recent research has shown that KLF10 attenuates tumor progression in multiple cancers by modulating the PTEN/AKT pathway." (PMID 34635142, 2021). "Collectively, these findings show that KLF10 is a tumour suppressor and is crucial for IR-induced apoptosis and DNA damage repair." (PMID 33485367, 2021). "Klf10 has been broadly implicated in epithelial to mesenchymal transition (EMT) as well as TGFβ signaling and is thought to function as a tumor suppressor gene." (PMID 34566577, 2021). "Several studies demonstrated the effect of KLF10 as a tumor suppressor via activation of p21 transcription, a well-known inhibitor of the cell cycle via CDK/cyclin inhibition and cell cycle arrest." (PMID 33233354, 2020). "There was a significant reduction in tumor formation in mice injected with KLF10-overexpressed MM cells when compared with NC (P < 0.05)." (PMID 32549754, 2020). "Conversely, KLF10 is a tumor suppressor that represses MYC expression in healthy cells and is involved in repressing proliferation and inducing apoptosis." (PMID 32945258, 2020). "SMAD7 and SKIL are well known as negative regulators of TGF-β signaling, and KLF10 is believed to play a crucial role as a tumor suppressor with unique tissue-specific functions mediated by TGF-β signaling." (PMID 32629802, 2020). "This is in contrast to many previous studies showing that KLF10 acts as a tumor suppressor through TGF signaling by playing an important role in induction of apoptosis." (PMID 32699233, 2020). "Conclusively, our results demonstrated that KLF10 functions as a tumor suppressor in regulating tumor growth of MM under regulation of miR-106b-5p, supporting its potential therapeutic target for MM." (PMID 32549754, 2020). "Many studies have shown that KLF10 acts as a tumor suppressor through TGF-β signaling by playing an important role in inhibition of cell proliferation and induction of apoptosis." (PMID 29799499, 2018). "Here, we reviewed KLF10 to understand its role and function in diseases, including cancer as a tumor suppressor, as well as its interaction with TGF-β signaling." (PMID 29799499, 2018). "Since KLF10 was first discovered, several studies have defined its role in cancer as a tumor suppressor." (PMID 29799499, 2018). "Taken together, the results of the studies discussed indicate that KLF10 can have profound effects as a tumor suppressor in many cancers via TGF-β/Smad dependent and independent pathways." (PMID 29799499, 2018). "KLF10 is believed to play a crucial role in inhibition of cancer cell proliferation and promotion of apoptosis, which strongly indicate its role as a tumor suppressor." (PMID 29799499, 2018). "KLF10, on the other hand, transcriptionally represses EGFR and inhibits invasion and metastasis in vitro and in an orthotopic mouse tumor model, and KLF10 loss is downregulated in invasive human BC." (PMID 25897424, 2015). "HES1 has been suggested to have both oncogenic and tumor suppressive functions, whereas KLF10 has been suggested to be a tumor suppressor gene." (PMID 24885297, 2014).
tumor (continued). "Interestingly, we also observed increased expression of KLF10 and JUP, genes typically associated with tumor-suppressive activity and cell-cell adhesion, respectively." (PMID 40950184, 2025). "In BCa, KLF10 has been proved to inhibit the tumor cell proliferation, migration and invasion." (PMID 38523597, 2024). "Through multivariable analysis, KLF10 loss was found to be associated with advanced PDAC stages and distant metastasis, revealing that the loss of regulatory repressive activity allows for uncontrollable growth that enhances tumor cell invasion and migration." (PMID 37239940, 2023). "A larger tumor size (p = 0.076) was found in patients with low expression of KLF10." (PMID 37308977, 2023). "Meanwhile, Opa interacting protein 5-antisense RNA 1 (OIP5-AS1) (tumor suppressive lncRNA) binds with miR-410 to prevent its expression, thus boosting cell proliferation and cellular activities by Krüppel-like factor 10 (KLF10)/PTEN/Akt axis in MM." (PMID 37987364, 2023). "The loss of KLF10 led to the upregulation of genes associated with EMT and tumor metastasis." (PMID 37946098, 2023). "The results suggest that the combination of metformin and evodiamine suppressed tumor growth of KLF10-deficient PDAC cells by elevating KLF10 and suppressing Notch-3/4 signals without any substantial toxicity." (PMID 37308977, 2023). "Conversely, the tumor suppressive role of KLF10 may vary depending on the tumor cells types and the microenvironments." (PMID 37958386, 2023). "KLF10 expression was inversely correlated with tumor stages." (PMID 35743973, 2022). "Moreover, a previous study reported that Klf10 plays an important role as a tumor suppressor, and overexpression of Klf10 downregulates cell proliferation in many cancers." (PMID 35915120, 2022). "Another tumor suppressor gene that shows aberrant methylation is Kruppel-like factor 10 (KLF10)." (PMID 34997020, 2022). "Previous studies indicated that KLF10 is a key tumor suppressor gene in multiple cancers." (PMID 36445338, 2022). "To explore whether KLF10 is involved in the FLVCR1-AS1-induced tumor inhibitory effects in PC, we first verified the effect of KLF10 on FLVCR1-AS1-induced inhibition of cell proliferation." (PMID 34635142, 2021). "In addition to the role in the regulation of metabolism, KLF10 also acts as a tumor suppressor through the TGF-β/Smad signaling pathway by inhibiting cell proliferation and inducing apoptosis." (PMID 34869587, 2021). "Krüppel-like factor 10 (KLF10) is a tumor suppressor in multiple cancers." (PMID 34702956, 2021). "Since KLF10 targets the promoter region of EGFR and inhibits EGFR transcription, we speculate that KLF10 might play a role in the synergetic anti-tumor effects of PDT/gemcitabine combination through inhibiting EGFR." (PMID 34805140, 2021). "Hypoxic tumour cell-derived exosomal miR-340-5p confers radioresistance in OSCC by targeting KLF10/UVRAG, suggesting that miR-340-5p could be a potential biomarker and therapeutic target for the enhancement of radiosensitivity in OSCC." (PMID 33485367, 2021). "Nevertheless, although the potential prognostic value of KLF10 was clearly demonstrated in our study, the detailed mechanism and molecular model of tumor suppression remain unclear and warrant further research." (PMID 33379261, 2020). "Taken together, our findings suggest that KLF10 acts as a tumor suppressor in MM progression." (PMID 32549754, 2020). "DEN-treated mice with KLF10 deletion exhibited increased levels of mesenchymal markers (N-cadherin and SNAI2) and tumor metastasis markers (matrix metalloproteinases 2 and 9)." (PMID 37946098, 2023). "One study investigating the connection between KLF10 expression and clinical features of PDAC found that mRNA expression was generally downregulated in primary tumor sites compared to surrounding normal pancreatic tissue." (PMID 37239940, 2023).
tumor (continued). "IHC of 31 and 29 tumor specimens, respectively, from the cohort of PDAC patients described in “Materials and methods”, also showed a trend of inverse correlation between KLF10 and NICD-3/4." (PMID 37308977, 2023). "Compared to para-tumor specimens, the mRNA levels of KLF5, KLF7, KLF8, and KLF13 were elevated, whereas those of KLF4, KLF6, and KLF10 were reduced in HCC specimens." (PMID 37554278, 2023). "miR-340-5p is directly transferred to normoxic OSCC cells and targets Kruppel-like factor 10 (KLF10), a tumour suppressor." (PMID 33485367, 2021). "For instance, we have reported that KLF10 was phosphorylated by CDK2 and Raf-1 at Ser206 and Thr93, respectively, further affecting the role of KLF10 in tumor suppression." (PMID 34869587, 2021). "The predicted binding and regulation between KLF10 and EGFR were verified, and the specific effects of KLF10 and EGFR upon the synergetic anti-tumor effects of PDT/gemcitabine combination were examined, respectively and combinedly." (PMID 34805140, 2021). "From a transcriptomic perspective, tumour endothelial cells upregulate angiogenesis-related genes, such as CD99, KLF10, and ADAMTS4, while losing scar tissue-related Notch molecule HES4 and antigen presentation molecule HLA-DRA." (PMID 33532508, 2021). "For example, KLF family proteins have been shown to have either a tumor-promoting (KLF4, KLF6, KLF9, KLF10, KLF11, and KLF17) or a tumor-suppressing (KLF5, KLF12) role by intervening in cell signaling associated with proliferation and/or suppression." (PMID 26320172, 2015). "In KLF10-depleted PDAC models, SIRT6 plays a pivotal role in reversing the malignant phenotypes, including increased EMT and glycolysis, which are characteristic of aggressive tumor progression." (PMID 39682281, 2024). "While immunohistochemistry revealed strong KLF10 expression in the non-tumor hepatocytes, the tumor site showed various intensities and extents of KLF10 staining." (PMID 37946098, 2023). "In addition, conditionally overexpressing KLF10 in MiaPaCa cells revealed that the levels of CD47, CD24, and CD44 expression on tumor cells were reduced by more than 50%." (PMID 37308977, 2023). "The combination of metformin, which upregulated KLF10 expression via phosphorylating AMPK, and evodiamine, a non-toxic Notch-3 methylation stimulator, delayed tumor growth of PDAC with KLF10 deficiency in mice without prominent toxicity." (PMID 37308977, 2023). "Despite a non-significant correlation with local tumor control and tumor size, partly due to small sample size, KLF10 was a significant prognostic factor for overall survival (p = 0.013) of this cohort of patients with resected PDAC." (PMID 37308977, 2023). "From tumor tissues of patients with resectable PDAC enrolled to a clinical trial, we demonstrated that the combination of KLF10 and SMAD4 expression in tumor tissues may help select those who may benefit the most from additional radiotherapy." (PMID 37958386, 2023). "For patients with resectable PDAC, a combination of KLF10 and SMAD4 expression in tumor tissues may help select those who may benefit the most from additional radiotherapy." (PMID 37958386, 2023). "IHC assays were then used to determine KLF10 protein levels in 25 PC tissues and paired non-cancerous tissues, revealing that KLF10 protein levels were lower in PC tissues than in paired non-tumor tissues." (PMID 34635142, 2021). "Our previous studies indicated that Raf-1 phosphorylated KLF10 leading to its destabilization by binding to peptidyl-prolyl cis–trans isomerase NIMA-interacting 1 (PIN1), thus decreasing the ability of KLF10 to inhibit tumor progression." (PMID 34869587, 2021).
tumor (continued). "In particular, we show that miR-548k regulates different hallmarks of cancer, including cell proliferation, migration, invasion, and tumor microenvironment remodeling through combinatorial regulating of multiple oncogenic routes, involving the ADAMTS1-VEGFC-VEGFR3 pathway and KLF10-EGFR axis." (PMID 30131072, 2018). "In addition, Cul4A knockdown increases the expression of KLF10, cyclin-dependent kinase inhibitor p21/WAF1, and TGF-β1, which play a role as tumor suppressors." (PMID 29799499, 2018). "IFNGR2, KLF10, PLAUR, MSN, and IKBIP, whose coefficients of risk score were >0, had positive correlations with risk score, stromal score, immune score, and ESTIMATE score and negative relationships with tumor purity." (PMID 38137116, 2023). "In contrast to targeting TGFβ, the therapeutic strategy of upregulating KLF10/SIRT6 signaling in PDAC may reduce distant metastasis without enhancing tumor proliferation." (PMID 34702956, 2021). "KLF10 may mimic the antiproliferative and proapoptotic effects of TGF-β1 on various tumor cells." (PMID 33233354, 2020). "Furthermore, we demonstrated that miR-548k modulating the tumor microenvironment by promoting VEGFC secretion and stimulating lymphangiogenesis through ADAMTS1/VEGFC/VEGFR3 pathways, while promoting metastasis by regulating KLF10/EGFR axis." (PMID 30131072, 2018).
cancer (44 papers, 2011 to 2025). A tumor composed of atypical neoplastic, often pleomorphic cells that invade other tissues. "In contrast to TGFβ in advanced cancers, loss of KLF10 was associated with rapid distant metastasis, relatively short survival, and resistance to radiotherapy." (PMID 37308977, 2023). "KLF10 was one of thirteen genes involved in the low-risk prognostic signature, relatively defined as improved prognosis and increased sensitivity to cancer treatment." (PMID 37239940, 2023). "The most significant DMRs associated with gene expression changes, include several cancer-related genes such as KLF10, GSTP1, MEGF10, SOX8 and IRX116–28." (PMID 34997020, 2022). "Our studies further revealed that loss of KLF10 increased distant metastases and cancer stemness through activation of SDF-1/CXCR4 and AP-1 pathways in PDAC." (PMID 31480737, 2019). "Another mechanism that may cause cancer-induced muscle wasting is primarily regulated by the TGF-β target gene known as KLF10." (PMID 38334644, 2024). "Hence, the loss-of-function of KLF10 has been identified as a promising approach to mitigate cancer-induced muscle atrophy." (PMID 38334644, 2024). "In conclusion, our study identified a BCa‐associated circRNA, circITGA7, and uncovered a novel anti‐cancer mechanism by which circITGA7 competitively interacts with miR‐330‐3p, subsequently leading to upregulation of KLF10 and inhibiting the growth and metastasis of BCa." (PMID 38523597, 2024). "However, the association between the expression of KLF10 and the clinical outcomes of patients with cancer remains controversial." (PMID 35743973, 2022). "Krüppel-like factor 10 (Klf10) has been described as regulators of muscle wasting in cancer (cachexia), and Klf5 was upregulated in atrophying myotubes as an early response to dexamethasone or simulated microgravity in vitro." (PMID 40649857, 2025). "On the other hand, the TGF-β pathway, along with the KLF10 positive feedback loop, activates cancer-associated fibroblasts (CAFs), thereby remodeling ECM and affecting cancer recurrence in lung adenocarcinoma." (PMID 39682183, 2024). "An in vitro experiment was performed to evaluate the role of KLF10 in the cancer microenvironment using Hep3B and LX2 cells." (PMID 37946098, 2023). "KLF10 expression in various cancer tissues has been reported to be significantly lower than that in normal tissues." (PMID 37958386, 2023). "Distinguishing the anti-proliferative functions from the pro-metastatic functions of TGFβ reveals KLF10 to be a potential target for the development of therapies for cancers with aberrant TGFβ pathways, such as PDAC." (PMID 37308977, 2023). "A spontaneous murine model of PDAC with additional KLF10 depletion reveals accelerated malignant progression and identifies a mechanism of cancer stem cell phenotype involving Notch signaling activation, suggesting a potential therapeutic target." (PMID 37308977, 2023). "KLF10 has been shown to mediate growth inhibition in cancer through anti-proliferative and apoptotic effects, while also blocking signaling pathways that ultimately reverse tumorigenic phenotype." (PMID 37239940, 2023). "In PDAC, KLF10 expression was low in two thirds of patients and was inversely correlated with the cancer stage." (PMID 37958386, 2023). "Several studies, including ours, have demonstrated that KLF10 transcriptionally suppresses the UV radiation resistance-associated gene (UVRAG) and modulates apoptosis, DNA repair, and autophagy in cancer cells." (PMID 37958386, 2023). "It appears that the soleus of Klf10 KO mice reproduces Warburg metabolism that is related to the functions of KLF10 described in the pathogenesis of various cancers." (PMID 35736488, 2022).